HDAC10 (histone deacetylase 10)
Diseases named in the same sentence as HDAC10 in open-access papers (continued):
Sharing a sentence is not in itself a finding about the gene and the disease.
cancer (continued). "Nonetheless, the studies reviewed herein demonstrate the promise of HDAC10 as a molecular target for cancer." (PMID 33997894, 2021). "HDAC10 has been reported to be involved in DNA mismatch repair, cell autophagy, and cancer progression." (PMID 33898439, 2021). "HDAC4 has been shown to be involved in immune regulation, while HDAC10 plays roles in DNA repair, autophagy and anti-cancer responses." (PMID 33898439, 2021). "In cancers, HDAC10 plays crucial roles in regulating various cellular processes through its epigenetic functions or targeting some decisive molecular or signaling pathways." (PMID 33997894, 2021). "Beyond targeting class IIb HDACs for therapeutic immunosuppression, our data also indicate a note of caution when considering HDAC10 as a therapeutic target in cancer, which has been suggested by several groups." (PMID 31949209, 2020). "Noticeably, we observed that the expression score of HDAC10 in NSCLC tissue of 180 patients was significantly higher than that in the corresponding para-cancer tissues (P < 0.001)." (PMID 32373519, 2020). "Positive immunostaining of HDAC10 was mainly located in the nucleus and cytoplasm of carcinoma cells." (PMID 32373519, 2020). "Five HDAC genes (HDAC2, HDAC4, HDAC5, HDAC10, and SIRT3) showed copy number loss in at least two cancer types." (PMID 30760718, 2019). "Our results indicate that certain HDAC genes (e.g., HDAC4 and HDAC10) focally lose copy numbers in selected cancer types." (PMID 30760718, 2019). "Here, we further investigated the role of HDAC10 in lysosome-related mechanisms, as it is becoming increasingly clear that lysosomes play an important role in cancer multidrug resistance (MDR)." (PMID 29968769, 2018). "We found that the cytoplasmic signal of HDAC10 in cancer tissue was higher than in normal tissue and that the difference between the signals was statistically significant." (PMID 27449083, 2016). "This is important with respect to understanding the mechanism by which HDAC10 functions in this type of cancer." (PMID 27449083, 2016). "Histone deacetylase 10 (HDAC10) is a member of the class II HDACs, and its role in cancer is emerging." (PMID 27449083, 2016). "These included several cancer-associated genes such as MKL1, EP300, NF2, and HIC2 and chromatin binding genes BRD1, HIRA, and HDAC10." (PMID 25909290, 2015). "By modulating autophagy through Hsp70 deacetylation, HDAC10 may help cancer cells survive under adverse conditions, but it could also push cells beyond their adaptive capacity, tipping the balance toward cell death." (PMID 39958888, 2025). "HDAC10 belongs to class IIb and is involved in a variety of cellular processes, including cell cycle, apoptosis, autophagy, and is gaining attention for its potential role in cancer cell biology." (PMID 39958888, 2025). "HDAC10 was investigated in different cancers, revealing its involvement in cell cycle regulation, apoptosis, and autophagy, but its role in CTCL is unknown." (PMID 39958888, 2025). "This presents a unique therapeutic opportunity where targeting HDAC10 could potentially enhance cancer cell vulnerability by disrupting their survival mechanisms, particularly in cancers that rely on autophagy for survival." (PMID 39958888, 2025). "Moving on, extensive research has demonstrated the significant involvement of HDAC10 in various facets of cancer biology, encompassing cell proliferation, apoptosis, metastasis, angiogenesis and drug resistance, albeit with distinct functions contingent upon specific cancer types." (PMID 38702756, 2024). "Role of Hdac10 in vertebrate development was not described up to date, however, mutations in Hdac10 were linked to poor prognosis regarding several cancer types." (PMID 34268305, 2021). "HDAC10 plays an essential role in the regulation of cancer cell growth." (PMID 33997894, 2021). "However, the nuclear signal of HDAC10 in cancer tissue was lower than in normal tissue, and the difference between the signals was statistically significant." (PMID 27449083, 2016).
cancer (continued). "The analysis yielded very interesting results that cytoplasmic HDAC10 expression in cancer tissue was significantly higher (p=0.0001) than in normal tissue, and nuclear HDAC10 expression in cancer tissue was significantly lower (p=0.0001) than in normal tissue." (PMID 27449083, 2016). "HDAC10 possesses HDAC activity and has been implicated in autophagy and cancer." (PMID 25487573, 2015). "Having uncovered HDAC10’s regulation in SPARC expression, we sought to explore its biological implications in cancer cells." (PMID 38650694, 2024). "Conversely, HDAC1, HDAC10, KAT2A, SIRT6, and SIRT7 were upregulated in 13, 16, 17, 14, and 12 cancer types." (PMID 39906742, 2024). "HDAC10 is a class IIb HDAC that plays critical roles in regulating cellular processes, genomic stability, cancer progression, cells autophagy, and stress response via its epigenetic functions 12-16." (PMID 37441601, 2023). "HDAC3, HDAC10, HDAC2, HDAC7, ATAD2B were significantly upregulated in 9, 14, 13, 9, and 10 cancer types, respectively, whereas KAT2B was downregulated in 16 cancer types." (PMID 37553641, 2023). "Thus, HDAC10 may be a potential target for the diagnosis and treatment of many cancers." (PMID 32373519, 2020). "The HDAC4, HDAC10, and SIRT3 copy numbers were recurrently lost in eight, six, and six cancer types, respectively." (PMID 30760718, 2019). "Interestingly, HDAC10 alone was down-regulated in HCC827 cells, but there was no change observed in HDAC2 or HDAC4 in either cancer cell line." (PMID 40941018, 2025).
infection (3 papers, 2008 to 2019). The state of being infected such as from the introduction of a foreign agent such as serum, vaccine, antigenic substance or organism. "We first detected the endogenous HDAC10 expression changes during HIV-1 (N119 strain) infection in the Jurkat T lymphocytes." (PMID 31888084, 2019). "Similar to A3G and BST-2, we found that HDAC10 levels decreased rapidly and were less than 50% at 48 h post infection." (PMID 31888084, 2019). "Expression of several histone deacetylases was also regulated during infection: HDAC2 and HDAC10 expression levels increased, while HDAC3, HDAC6, and HDAC9 expression decreased." (PMID 18331636, 2008). "Intriguingly, the levels of 2-LTR DNA decreased to 50%–70% in HDAC10-KD cells at 24 h post-infection, implying that the high level of integrated DNA was not due to an increased DNA nuclear import." (PMID 31888084, 2019).
inflammation (2 papers, 2018 to 2024). Aberrant reaction of the microcirculation characterized by movement of fluid and leukocytes from the blood into extravascular tissues. "Hdac10 deficiency attenuates LPS-induced lung inflammation in ALI." (PMID 38956592, 2024).
HDAC10 also shares sentences with these, for which no sentence is quoted: clear cell renal carcinoma (2 papers); colon adenocarcinoma (2); adenoma (1); adult T-cell leukemia (1); alcoholism (1); Bladder Urothelial Carcinoma (1); chronic hepatitis B infection (1); chronic lymphocytic leukemia (1); endocervical adenocarcinoma (1); head and neck cancer (1); hyperplastic polyp (1); inflammatory skin disease (1); liposarcoma (1); liver cancer (1); lymphoblastic leukemia (1); pulmonary arterial hypertension (1); pulmonary fibrosis (1); skin cancer (1); squamous cell carcinoma (1); stomach cancer (1); systemic lupus erythematosus (1); T-cell leukemia (1); testicular cancer (1); thyroid cancer (1).